PLA2G2D (phospholipase A2 group IID)
Diseases named in the same sentence as PLA2G2D in open-access papers (continued):
Sharing a sentence is not in itself a finding about the gene and the disease.
tumor (27 papers, 2008 to 2026). "PLA2G2D is known for its involvement in inflammatory signaling and has been shown to modulate dendritic cell function and T-cell recruitment in the tumor microenvironment." (PMID 41529246, 2026). "Macro-PLA2G2D functioned in antigen processing presentation, monocyte chemotaxis and complement activation, while PLA2G2D can exert promotional effects on tumor progression and angiogenesis." (PMID 39239507, 2024). "The 63 upregulated genes, including PLA2G2D, IFNG, LAG3, CD8B and NKG7, were associated with tumor immunity." (PMID 35530341, 2022). "PLA2G2D, IFNG, CD8B and NKG7 were found to be significantly upregulated, which are associated with tumor immunity." (PMID 35530341, 2022). "Our findings along with growing literature, together suggest that future investigations to elucidate the mechanistic role of PLA2G2D in tumor contexts will enrich our understanding of tumor immunobiology." (PMID 34446728, 2021). "More importantly, PLA2G2D-high tumors also exhibited higher infiltration of CD8+ T cells inside the tumor region than PLA2G2D-low tumors." (PMID 34733790, 2021). "Previous studies have reported that PLA2G2D and ST3GAL5 may be potential tumor biomarkers associated with immune cells." (PMID 37205993, 2023). "Together, this data suggest the potential of PLA2G2D as a biomarker of tumor immunity." (PMID 34446728, 2021). "PLA2G2D is an immune regulator that participates in the transformation of lipid balance to an anti-inflammation status and can either have a beneficial or detrimental function, contingent on the inflammation and tumor context." (PMID 34966691, 2021). "Therefore, it would be interesting to elucidate how the coordination of FABP7, ACSL4 and PLA2G2D in tumour microenvironment modulates the remodelling of membrane lipids as well as tumour immunity." (PMID 31819188, 2020). "In clear contrast, the genes involved in FA desaturation (stearoyl-CoA desaturase, SCD5) and PUFA trafficking (fatty acid-binding protein 7, FABP7; acyl-CoA synthetase 4, ACSL4; phospholipase A2G2D, PLA2G2D) were upregulated in tumours with PI(18:0/20:3) accumulation." (PMID 31819188, 2020). "Up-regulation of the genes Tnf-α, Nf-κB as well as Pla2g2d (Phospholipase A2 group IID), known to be implicated in pro-inflammatory mediation, indicates an early immune response that may be related to SHE cell transformation and tumor promotion." (PMID 36982734, 2023). "We discovered five tumor antigens (P2RY6, PLA2G2D, RBM47, SEL1L3, and SPIB) that are significantly increased and mutated, which correlate with the survival of patients and the presence of immune cells that present these antigens." (PMID 40066453, 2025). "The main findings of the current research identified 3 immune-related genes (PLA2G2D, TNFAIP8L2, and CYP27A1) which are likely to play highly significant roles in lipid metabolism-mediated tumor immunity regulation in HNSC." (PMID 37210507, 2023). "Among the upregulated genes, PLA2G2D and SIGLEC15 had a putative function in immunosuppression or promoting tumor growth and metastasis." (PMID 34722496, 2021). "Similar data were obtained for samples from the right colon, with a 22-fold increased expression in tumour vs normal mucosa for PLA2G3, and 10- and 44-fold reduced expression for PLA2G2D and PLA2G5, respectively." (PMID 18212756, 2008). "A similar report pointed out that PLA2G2D positively correlated with CD8+T cells, M1 macrophages and CD4+ memory activated T cells and negatively correlated with M2 macrophages, suggesting its potential anti-tumor effect." (PMID 39239507, 2024). "Importantly, in the tumor region, CD8+ TILs were the only cell population that were more frequently observed in the PLA2G2D high-expression group." (PMID 34733790, 2021). "Our results demonstrated that CXCL13, FCRLA, MS4A1, and PLA2G2D have a negative correlation with tumor purity in OC." (PMID 34395521, 2021).
tumor (continued). "Moreover, in the tumor region, only CD8+ TIL density in the PLA2G2D high-expression group was higher compared with that in the PLA2G2D low-expression group." (PMID 34733790, 2021). "Three immune genes (PLA2G2D, TNFAIP8L2, and CYP27A1) and immune-related pathways (T cell receptor signaling, Th17 cell differentiation, and natural killer (NK) cell mediated cytotoxicity) were predicted to play significant roles in the lipid metabolism-mediated tumor immunity in HNSC." (PMID 37210507, 2023). "The current research identified immune genes PLA2G2D, TNFAIP8L2, and CYP27A1 and immune cells-related pathways T cell receptor signaling, Th17 cell differentiation, and NK cell mediated cytotoxicity as the primary candidates involved in lipid metabolism-mediated tumor immunity in HNSC." (PMID 37210507, 2023).
infection (8 papers, 2013 to 2025). The state of being infected such as from the introduction of a foreign agent such as serum, vaccine, antigenic substance or organism. "Two additional sPLA2 enzymes, PLA2G2D and PLA2G10, are also upregulated in the lungs of mice infected with influenza virus and are implicated in exacerbating infection outcomes." (PMID 39596471, 2024). "Several genes were significantly upregulated (Pla2g4a, Pla2g4c, Pla2g7, Ptgs1, Ptgs2, Pla1, Tbxas1) or downregulated (Alox5, Pla2g2d, Pla2g1b, Pla2g4b, Pla2g4f) during infection." (PMID 35812400, 2022). "Additionally, 46 genes encoding for secreted proteins may serve as markers in blood for the degree of protection (Cxcl9, Gp2, and Pla2g2d), intensity of infection (Retnla, Saa3, Il6, and Il1b), or adaptive recall responses (Ighg, C1qb)." (PMID 28243609, 2017). "Strikingly, infection of mice lacking PLA2G2D (Pla2g2d (−/−) mice) converted a uniformly lethal infection to a nonlethal one (> 80% survival), together with enhanced antivirus T cell responses and diminished lung damage." (PMID 32897518, 2021). "Strikingly, middle‐aged mice lacking expression of DPr1 or PLA2G2D are protected from severe disease in a model of SARS‐CoV‐2 infection and a DPr1 antagonist, asapiprant, protected aged mice from lethal infection." (PMID 37948331, 2023).
metabolic disease (4 papers, 2016 to 2022). A congenital disorder (due to inherited enzyme abnormality) or acquired (due to failure of a metabolically important organ) disorder resulting from an abnormal metabolic process. "PLA2G2D increased energy expenditure and thermogenesis by promoting adipocyte browning, thereby improving diet-induced metabolic disorders." (PMID 36518097, 2022).
adenocarcinoma (1 paper, 2008). A common cancer characterized by the presence of malignant glandular cells. "A marked decrease in the expression level of PLA2G2D and PLA2G5 was observed in both left- and right-sided adenocarcinomas." (PMID 18212756, 2008). "In adenocarcinomas from left and right colon, the expression of PLA2G3 was increased by up to 40-fold, while that of PLA2G2D and PLA2G5 was decreased by up to 23- and 14-fold." (PMID 18212756, 2008).
PLA2G2D also shares sentences with these, for which no sentence is quoted: atherosclerosis (7 papers); asthma (4); Arthritis (3); chronic obstructive pulmonary disease (3); colitis (3); colon cancer (3); Alzheimer disease (2); angioedema (2); COVID-19 (2); head and neck squamous cell carcinoma (2); metabolic syndrome (2); metastatic tumor (2); rheumatoid arthritis (2); Sepsis (2); acute pancreatitis (1); allergic asthma (1); Allergy (1); autoimmune myocarditis (1); bacterial infections (1); Bovine mastitis (1); cardiovascular disease (1); contact dermatitis (1); coronary heart disease (1); cutaneous melanoma (1); dengue haemorrhagic fever (1); diabetes (1); esophageal cancer (1); glaucoma (1); heart disease (1); Hepatic steatosis (1).
A further 15 diseases each share a sentence with PLA2G2D in 1 paper.